CD44 (CD44 molecule (IN blood group))
Diseases named in the same sentence as CD44 in open-access papers (continued):
Sharing a sentence is not in itself a finding about the gene and the disease.
breast carcinoma (continued). "CD44 is also a well-known surface biomarker of CSCs, and any anomalous expression or dysregulation of CD44 may indicate tumorigenesis and metastasis in multiple cancers such as colon, bladder, gastric, lung, and breast cancers." (PMID 36289750, 2022). "Indeed, a xenograft study using nude mice and other in vivo experiments have reported that disseminated tumor cells in the bone marrow of breast cancer patients showed a high CD44+/CD24- ratio and the elevated expression of CD44+/CD24- was closely associated with lung metastasis." (PMID 33861751, 2021). "Likewise, a meta-analysis to address the prognostic significance of CD44 expression in breast cancer showed no noteworthy association between CD44 and OS or DFS." (PMID 34944493, 2021). "The examination of a model for breast cancer tumor progression and of a cohort of patients with acute lymphoblastic leukemia (B ALL) further substantiated the correlation between the level of intragenic CD44 methylation and that of CD44 variant intron inclusion." (PMID 34086943, 2021). "Moreover, as to Kong, serum level of CD44 in triple negative subtype was remarkably higher than that in luminal subtype, which could function as an independent prognostic factor in breast cancer." (PMID 34801088, 2021). "Furthermore, apigenin reduces number of CD44+ cells in breast cancer." (PMID 34769099, 2021). "However, the exact roles of CD44 remain unclear in breast cancer as both high and low levels of the marker are correlated with tumor-promoting and tumor-suppressing outcomes." (PMID 34579762, 2021). "It has been shown that the increased expressions of CD44 in the breast cancer tissues determine the tumor progression and metastasis, and the CD44 could weaken the adhesion between tumor cells and enhance the matrix adhesion, promoting the tumor cell migration and metastasis." (PMID 34932597, 2021). "Additionally, we tested whether the detached cells express stemness surface markers for breast cancer stem-like cells (CD44+/CD24−) using flow cytometry." (PMID 34725457, 2021). "However, CD44+/CD24−/low BCSC abundance was found to differ in breast cancer subtypes." (PMID 33801148, 2021). "Therefore, this indicates that the CD44–NRF2 axis might be an effective therapeutic target to impair the stress resistance and survival of the CD44 high CSC population in breast cancer, in agreement with the previous findings." (PMID 33805996, 2021). "Moreover, in primary breast cancer, a direct interaction between CD44 and CD74 has been described." (PMID 34209696, 2021). "An ADC consisting of an anti-CD44 antibody (Bivatuzumab) bound to mertansine was tested in phase I clinical trials for head and neck and esophagus squamous cell carcinomas and for breast cancer, but the trials had to be terminated before progression to phase II due to severe skin toxicities." (PMID 33081391, 2020). "It is plausible that combining chemotherapy with agents that inhibit CD44 on TMPs may reduce the potential for metastasis, and therefore can serve as a strategy to inhibit the possible risks of chemotherapy-induced metastasis in breast cancer." (PMID 33050539, 2020). "Therefore, the purpose of this study was to explore whether disruption of CD44 cross-linking in breast cancer cells could prevent the cells migration and invasion and determine the effects of CD44 cross-linking on the malignancy of the cancer cells." (PMID 33292278, 2020). "In turn, CD44 adheres to its ligand and leads to the activation of src and phosphorylation of cortactin, thus, supporting that Nav1.5 may potentiate the invasion of breast cancer cells by the CD44-src-cortactin signaling axis." (PMID 32792949, 2020). "Indeed, CD44, integrins and DDRs are overexpressed in breast cancer and promote tumor progression." (PMID 32984031, 2020).
breast carcinoma (continued). "These cells can be enriched in vitro by growing them as mammospheres, which are 3-dimensional spherical breast cancer cell colonies that grow in suspension in serum-free, growth-factor-enriched media and are characterized by the expression of specific cell surface markers, such as CD44+/CD24−/low." (PMID 32444778, 2020). "Moreover, these AML cells could be enriched by using a combination of the cell surface markers CD34+CD38-2, while breast cancer-propagating cells were marked with CD44+CD24-/low3." (PMID 32754274, 2020). "Future studies on the role of CLSTN1 splice isoforms in breast cancer metastasis will be necessary to determine whether this splice isoform switch is functionally important for metastasis, as we previously uncovered for the CD44 splice isoform switch." (PMID 31980632, 2020). "However, different studies raised concerns whether the CD44+/CD24−/low phenotype would be a good marker profile for predicting breast cancer stem/ initiating cells." (PMID 32430004, 2020). "As CD44 is known to be overexpressed on BCSCs, surface marker-targeting ligand-conjugated drug delivery systems, such as liposomes, could be used to target BCSCs and enhance the overall therapeutic efficacy of drugs against breast cancer." (PMID 33255298, 2020). "Our results reinforce the potential relevance of CD44 as a potential marker of breast cancer as well as propose other proteins that might play key roles as biomarkers such as CST3, which needs to be extensively and individually studied in the serum of large series of patients." (PMID 33224883, 2020). "Similarly, activation of epidermal growth factor receptor (EGFR) leads to an expansion of CD44+/CD24− populations in TNBC (which is heavily enriched in basal-like breast cancer) in a mitogen-activated protein kinase kinase/extracellular signal-regulated kinase (MEK/ERK) dependent manner." (PMID 32391382, 2020). "EV-miR-23b from BMSCs reduces the proliferation, sensitivity to docetaxel and CD44, a stem cell marker, of bone marrow–metastatic breast cancer (BC) cells by targeting MARCKS, thereby contributing to dormancy of BC stem cells in metastatic niches." (PMID 32503543, 2020). "In addition, 66.45 ± 1.63% of CD44+/CD24− subgroup of breast cancer cells were TS+ cells." (PMID 31253779, 2019). "IL-6 secretion is crucial for CSC maintenance and sufficient to induce the CD44 + /CD24 low phenotype in breast cancer cell lines and tumors, this supporting the idea that the IL-6-JAK2-STAT3 signal transduction pathway could play an important role in the conversion of non-CSCs into CSCs." (PMID 30728463, 2019). "To test whether SRSF1 could regulate the alternative splicing of CD44 in GC cells, as it was reported in breast cancer cells, we detected the relative levels of different CD44 isoforms in MGC-803 cells transfected with siRNA specific to SRSF1 or negative control." (PMID 31857793, 2019). "Hypothetical CSC2s might be the CSCs with an ALDH1+ CD44- Ki67+ profile detected in mammary tumors." (PMID 30899759, 2019). "Our previous study revealed a linear correlation between CD44 expression level in invasive breast cancer (BC) and tumor grade." (PMID 30691317, 2019). "Therefore, we hypothesized that CTLs stimulated by DCs pulsed with CD44 peptide can recognize the CD44 naturally present in breast cancer cells in the context of HLA-A2 and kill CD44 positive MCF-7 tumor cells." (PMID 29298343, 2018). "This suggests GLO1 may be function in CD44-positive CSCs in luminal A breast cancers." (PMID 30559934, 2018). "It is reported that CD44 rs353639 variant may associate with breast cancer prognosis; however, both the rs13347 and rs353639 polymorphisms did not affect breast cancer risk in a North Indian population." (PMID 29483847, 2018).
breast carcinoma (continued). "Consistent with the observations in breast cancer tissues, there was an inverse association between expression level of CRB3 protein and expression levels of β‐catenin protein, β‐catenin downstream factors (CD44 and cMyc) and cancer stem cell‐associated transcription factors (OCT4 and NANOG)." (PMID 29602199, 2018). "However, the clinical impact of CD24 and CD44 expression in tumours remains unclear, and further investigation will be necessary to evaluate the correlation between ER expression and CD44+/CD24− cells in breast cancer." (PMID 29986702, 2018). "Therefore, we consider the CD44+/CD24− MDA-MB-231 cells as being more breast cancer stemcell-like." (PMID 29510720, 2018). "In addition, we investigated whether a relationship exists between CD10 expression and breast cancer stem cell immunophenotype (CD44+/ALDH1+)." (PMID 29306324, 2018). "Finally, we determined that IBC could enhance the sensitivity of paclitaxel‐resistant breast cancer cells and reduce the growth of xenograft tumours via the regulation of CD44 expression." (PMID 30179299, 2018). "Moreover, in breast cancer CD44 has been related to both tumor suppression and promotion." (PMID 28910304, 2017). "Subsequently, CSCs were identified in solid tumours by Al-Hajj and co-workers who reported in 2003 that only a subpopulation of breast cancer cells staining, positively for CD44 and negatively for CD24, could re­ initiate tumours with the cellular heterogeneity typical of the original tumour." (PMID 29211293, 2017). "However, ESRP1 may also promote lung metastasis of orthotopically transplanted breast cancer cells by generating CD44 isoforms independently of EMT." (PMID 28975893, 2017). "Collectively, our study indicated that CD44 might be a novel target of DACH1 in breast carcinoma." (PMID 28659634, 2017). "Furthermore, alternative splicing of CD44 and several other genes in breast cancer cell lines contributes to the epithelial-to-mesenchymal switch and may promote metastasis." (PMID 28263985, 2017). "Moreover, a significant decrease in the CD44 population was noted in basal-type breast cancers." (PMID 29100426, 2017). "Recently, in the period of studying roles of fibroblasts on cancer cells, we found that CD44 expression level was very high in fibroblasts; thus, we suggested that the fibroblasts with high CD44 expression may play important roles in the effect on breast cancer cells." (PMID 28523716, 2017). "Thus, it is reasonable that combined utilization of ACTN4 and CD44+/CD24− markers might be more sufficient to isolate metastatic cells with CSC properties in breast cancer." (PMID 29197410, 2017). "In addition, FOXA2 could maintain breast cancer stem cells, and downregulating it in these cells reduced the formation of spheres and the expression of CD44, ALDH1." (PMID 29187221, 2017). "However, the identification of CD44 as a marker of breast cancer stem cells has led to the development of a novel strategy through which to target CD44 and, thus, the subpopulation of stem-like cells that may reside in such tumors." (PMID 27379207, 2016). "Moreover, MFB inhibits the mammosphere formation of breast cancer cells and shows cytotoxic effects against CD44+CD24−/low populations in vitro and in vivo, indicating that it might have preferential effects on the cancer stem cell population." (PMID 27223262, 2016). "Therefore, we next investigated whether the WNT5A-mediated reduction in CD44 decreased PI3K/AKT signaling in breast cancer cells." (PMID 27623766, 2016). "Furthermore, CD44+CD24−/lo breast cancer cells are characteristics of breast chemoresistant CSCs." (PMID 27659530, 2016). "However, substantial levels of CD44 are found in other breast cancer cells." (PMID 27029001, 2016).
breast carcinoma (continued). "Indeed, CD44 has been amply reported as a marker that identifies breast cancer cells with a pronounced self-renewal and metastatic potential and, interestingly, circulating tumor cells endowed with metastatic capabilities have been shown to highly express the CD44 isoform variant, CD44v6." (PMID 27494839, 2016). "Likewise, mesenchymal-like breast cancer cells that displayed higher resistance to radiation than their parental epithelial-like cells, were also found to exhibit a stem cell-like phenotype including a CD44+/CD24-/low molecular signature." (PMID 26988558, 2016). "Finally, the pre-incubation of CD44+ 4 T1 murine breast cancer cells with sE-selectin augmented infiltration into the lung in E-selectin K/O mice and infusion of human PBMCs pre-incubated with sE-selectin stimulated MDA-MB-231 xenografted breast tumor growth in NSG mice." (PMID 27220365, 2016). "Virtually all of the EpCAM+ and/or CD90+ selected cells coexpressed CD44, a marker associated with epithelial-to-mesenchymal transition and tumorigenic breast cancer stem cells, and CD146 (not shown, 83.5±9.8%), a marker associated with epithelial-to-mesenchymal transition in breast cancer." (PMID 28721373, 2016). "Notably, Å6 inhibited the migration of a subset of ovarian and breast cancer cell lines in vitro by inducing high adhesion of the CD44-expressing cells to an HA substrate and altering CD44 conformation, obviously locking the cells to substrates of HA, abundantly found, e.g., in LNs." (PMID 25941526, 2015). "In addition, reports have confirmed that in both breast cancer-derived cell lines and breast tumors, CD44+CD24− phenotypes were not necessarily associated with patient outcome or the ability to metastasize." (PMID 25905435, 2015). "In the current study we demonstrated by genomic screening that CD44 expression is enhanced in aggressive (vasculogenic, VM+) tumor cells, as compared to non-aggressive (non-vasculogenic, VM−) tumor cells derived from both Ewing sarcoma and breast carcinoma tissues." (PMID 26189059, 2015). "For example, it was found that, in breast cancer cells, CD44 may act as a metastatic suppressor gene when it is influenced by reactive oxygen species (ROS), as seen by decreased CD44 protein expression in the Alpha5 cell line in a compensatory response to increased MnSOD protein expression." (PMID 26448753, 2015). "Similarly, mTOR inhibitor rapamycin chemically conjugated to HA nanoparticles via a novel sustained-release linker, 3-amino-4-methoxy-benzoic acid was found to slow down the clearance of rapamycin by 8.8-fold in immunocompetent mice bearing CD44-positive 4T1.2neu breast cancer cells." (PMID 25954275, 2015). "In addition to antibody-based targeting of CD44, other strategies have been employed using DNA aptamers targeting CD44v10 in breast cancer and peptides mimicking CD44v6 for blocking the coreceptor function of CD44v6 for c-Met and VEGFR-2 in endothelial cells thereby impeding angiogenesis." (PMID 26569327, 2015). "Interestingly, our results take on added clinical significance when one considers that this study and other recent reports indicate that CD44 expression is especially enriched in ER-negative, PR-negative and/or Her2-negative breast cancers which have the worst clinical prognosis and outcome." (PMID 25888636, 2015). "It has been considered that CD44+/ CD24−/low cells or P63+ cells were mainly associated with the CSCs of basal cell origin of ductal carcinoma, however, the characteristics and markers of luminal cell-derived breast cancer CSCs remains unclear." (PMID 26472025, 2015). "However, MDA-MB-231 breast cancer cells also had 76.6% CD44+CD24−/low cells, indicating that the CD44+CD24−/low subpopulation may encompass stem cells with self-renewal and other cell types without this property." (PMID 25405855, 2015).
breast carcinoma (continued). "However, it is important to stress that this current analysis has reaffirmed our correlation of CD44 to ER- and PR-null tumors, linking high CD44 expression to basal-like breast cancer, a subtype of this disease known to have the worst prognosis and most aggressive form of disease." (PMID 25888636, 2015). "Moreover, breast cancer initiating cells display down-regulation of ERα and clonal expansion of these CD44+/CD24low/−/ERαlow/− cancer cells may be responsible for tumor recurrence and development of distant metastases of initially ERα+ breast carcinomas." (PMID 24816249, 2014). "We hypothesized that specific inhibition of ALDH by DEAB may sensitize the ALDH-sorted fractions of the three MPM cell lines as DEAB has been shown to inhibit ALDH in breast, leukemia and lung cancer cell lines, as well as the ALDHhigh/CD44+ cells in breast cancer." (PMID 24884875, 2014). "Also, HER2 can be clinically correlated with stem/progenitor cell populations in that patients with HER2+ breast cancers treated with the HER2 inhibitor lapatinib show a significant reduction in the number of CD44+/CD24–/low cells and a decreased tumorsphere-forming efficiency." (PMID 25209720, 2014). "Indeed, LMW-HA plays an important role in CD44-TLR-associated AFAP-110-actin interaction and MyD88-NF-κB signaling required for tumor cell behaviors, which may contribute to the progression of breast cancer." (PMID 25140302, 2014). "Furthermore, we isolated CD44+/CD24− breast CSC from a breast cancer cell line and examined whether simultaneous modulation of both Oct-4 and/or Nanog expression could alter the expression of EMT-related molecules and invasiveness of CSC in vitro." (PMID 25301732, 2014). "Because CIN in breast cancer is mechanistically linked to development of centrosome abnormalities, we analyzed the grade of centrosome amplification in bulk SUM149PT cancer cells versus the stem-like CD44+/CD24−/Low subpopulation isolated by FACS sorting assay." (PMID 24970653, 2014). "Furthermore, CD44 localisation in lipid rafts and levels of palmitoylation in nontumour versus invasive breast cancer primary cultures supports the conclusions we have made in normal-like versus highly invasive breast cancer cell lines." (PMID 24512624, 2014). "Cell populations enriched with breast cancer stem cells can be identified by expression of specific sets of marker proteins such as nucleostemin and aldehyde dehydrogenase-1 (ALDH-1), which are associated with maintenance and self-renewal properties, and by their CD44+/CD24-/low phenotype." (PMID 25209720, 2014). "Similar to high CD44 levels, increased expression of LSR has been associated with altered gene expression of pathways involved in transformation and tumorigenesis, enhanced proliferation, survival in anchorage independent conditions and promotion of collective cell migration in breast cancer cells." (PMID 24990559, 2014). "Consequently, in this manuscript we specifically investigate whether regulation of the subcellular localisation of CD44 could account for its regulation of breast cancer cell migration (an early event in the metastatic cascade)." (PMID 24512624, 2014). "Interestingly, it was recently published that autophagy promotes the undifferentiated stem-like CD44+/CD24-/low phenotype in breast cancer cells and further evidence for the involvement of autophagy in cancer stem-like cell maintenance as well as their differentiation is accumulating rapidly." (PMID 24229464, 2013). "Therefore, the development of therapies eliminating CD44(+)/CD24(-/low) CSCs or impeding activation of the signaling pathways these cells rely on may represent a promising approach for basal-like breast cancer." (PMID 24392029, 2013).